AQP2 (aquaporin 2)
Diseases named in the same sentence as AQP2 in open-access papers (continued):
Sharing a sentence is not in itself a finding about the gene and the disease.
cyst (21 papers, 2014 to 2026). A sac-like closed membranous structure that may be empty or contain fluid or amorphous material. "In ADPKD, altered localization or reduced expression of AQP1 and AQP2 disrupts standard water transport mechanisms, contributing to cyst formation and progression." (PMID 40428321, 2025). "Our results correspond with formerly published observations regarding AQP1 and AQP2 and their role in cyst formation and development." (PMID 40428321, 2025). "In contrast, postnatal Tsc1 KO mice with Aqp2-Cre exhibited later cyst progression after 4 to 8 weeks of age." (PMID 36627370, 2023). "The H+-ATPase expression in Pkd1 mice is shown for comparison and indicates a completely different pattern, with few cells lining the cysts expressing H+-ATPase, whereas labeling with AQP-2 is very robust in cyst epithelia in Pkd1 mutant mice." (PMID 38028758, 2023). "AQP2 has also been shown to play a role in the development of renal cysts, where overexpression of AQP2 promotes cyst formation." (PMID 34843700, 2022). "We validated the clustering outcomes by using specific antibodies for different nephron segments, including LRP2, SLC12A1, CDH16, KRT17 and two classical markers CD10 and AQP2(the marker of PT and CD, respectively) for IHC staining of cyst epithelial cells." (PMID 34815804, 2021). "In one study, steviol slowed cyst growth by reducing AQP2 expression and promoting AQP2 degradation in vitro." (PMID 30654539, 2019). "Several principal cells and numerous intercalated cells are present in cyst epithelium as verified by the expression of AQP‐2 (green) and H+‐ATPase (red), respectively, in distinct cells." (PMID 30675765, 2019). "Aquaporin 2 (AQP2) is involved in fluid secretion, promoting cyst enlargement in polycystic kidney disease (PKD)." (PMID 29937486, 2018). "On the other hand, the overexpression of AQP2 has been described to enhance cyst enlargement." (PMID 40428321, 2025). "Moreover, overexpression of aquaporin 2 (AQP2) was shown to be involved in fluid secretion, leading to cyst enlargement in ADPKD." (PMID 37675342, 2023). "To identify the tubular segment involved in cyst formation, we stained for different tubular segment markers, i.e., aquaporin 2 (AQP2) for collecting ducts, CD13 and aquaporin 1 (AQP1) for proximal tubules and Tamm–Horsfall protein (THP) for the thick ascending limb (TAL)." (PMID 35055068, 2022). "Thus, steviol reduced AQP2 expression by reducing AQP2 transcription and promoting proteasome and lysosome-mediated AQP2 degradation, sequentially slowing cyst growth." (PMID 33986666, 2021). "There are very few AQP‐2 positive cells in cyst epithelia in 11 weeks old Aqp2CreTsc2 mice." (PMID 30675765, 2019). "Interestingly, the H+‐ATPase‐positive cells (white arrows) are more abundant compared to AQP‐2 positive cells (yellow arrows) in cyst epithelium." (PMID 30675765, 2019). "Thus, this cyst type may precede the formation of AQP1- or AQP2-positive cysts and may represent the earliest manifestation of the disease, although long-term monitoring is required for definite proof." (PMID 31822676, 2019). "To assess the cyst-inhibitory effect of HL156A in vivo, we generated Pkd1 conditional knockout (KO) mice with aquaporin 2 (AQP2)-Cre, which selectively expresses Cre recombinase in the collecting duct." (PMID 39062520, 2024). "Aquaporin 2 (AQP2) is involved in fluid secretion in ADPKD and promotes cyst enlargement." (PMID 33986666, 2021). "AQP‐2 expression was present in non‐cystic tubules but surprisingly was absent in cyst epithelial cells in Aqp2CreTsc2 mice." (PMID 30675765, 2019). "The cyst location was determined by IHC staining for AQP1 and AQP2." (PMID 30235266, 2018). "However, miR-182-5p inhibition could not slow cyst growth in Pkd2f/f:Aqp2-cre mice because Wasf2, Dock1, and Itga4 play significant roles in Pkd1 but not in Pkd2 conditional KO mice." (PMID 29074972, 2017).
cyst (continued). "Regardless of the presence of cysts, AQP2 was primarily localized to the subapical compartment of the cytosol in ADPKD tubules and cyst epithelia." (PMID 40763312, 2025). "However, kidney to body weight ratio, cystic index and cyst size of both LTL+ and AQP2 + cysts were not significantly different between Pkd1 cko and Dko female mice, unlike in males." (PMID 41474822, 2025).
acute kidney injury (17 papers, 2013 to 2025). Sudden and sustained deterioration of the kidney function characterized by decreased glomerular filtration rate, increased serum creatinine or oliguria. "In an experimental model of acute kidney injury, Fernandez-Llama and colleagues and Kwon and colleagues found that ischemia, which is associated with mt dysfunction, resulted in decreased AQP2 expression and urinary dilution." (PMID 39361429, 2024). "In kidney AQP2 expression is downregulated during sepsis and can cause renal failure." (PMID 29449936, 2018). "A cecal ligation and puncture (CLP) mouse model for sepsis showed that Aqp2 expression is downregulated through NF-κB pathway and may therefore cause acute renal failure during sepsis." (PMID 29449936, 2018). "We have previously shown that a higher dose of 5000 mg/kg of adenine caused the downregulation of AQP2 and NKCC2, which resulted in significant salt and water wasting before the onset of renal failure." (PMID 40794384, 2025). "In contrast, only 8 out of 82 recipients (10%) with an AQP2 abundance in uEVs of less than 2.00 compared to the controls showed acute kidney injury (p = 0.0003 by Fisher’s exact test)." (PMID 39334890, 2024). "Our results showed that the median ratio of principal cell-specific AQP2 abundance in uEVs was significantly higher in deceased-donor recipients with acute kidney injury than in immediate allograft function." (PMID 39334890, 2024). "The findings indicated that elevated miR-34b-5p levels in septic acute kidney injury (AKI) patients were associated with inflammation and apoptosis through the downregulation of AQP2, a direct target of miR-34b-5p." (PMID 39544938, 2024). "A total of 16 out of 82 recipients (20%) with an AQP2 abundance in uEVs greater than 2.00 compared to the controls showed acute kidney injury." (PMID 39334890, 2024). "In a sepsis-induced acute renal failure mouse model, AQP2 expression was downregulated through the NF-κB pathway, and NF-κB is a downstream transcription factor of the p38 MAPK signalling pathway." (PMID 31529146, 2019). "AQP2 abundance using specific AQP2 antibody 19-64-17 was significantly higher in kidney transplant recipients with acute kidney injury (median 0.20; IQR 0.09 to 0.28) compared to immediate allograft function (median 0.08; IQR 0.04 to 0.18; p < 0.01 by Mann–Whitney test)." (PMID 39334890, 2024). "In conclusion, determining principal cell-specific AQP2 abundance in uEVs early in the first postoperative day quantifies principal cell damage after kidney transplantation and is a non-invasive predictor for acute kidney injury." (PMID 39334890, 2024). "AQP2 abundance using specific AQP2 antibody 19-65-1 was significantly higher in kidney transplant recipients with acute kidney injury (median 0.17; IQR 0.09 to 0.24) compared to immediate allograft function (median 0.09; IQR 0.06 to 0.15; p < 0.05 by Mann–Whitney test)." (PMID 39334890, 2024). "Interestingly, reducing the activation of NF-κB signaling ameliorated the downregulation of AQP2 protein and sepsis-induced acute renal failure." (PMID 30654539, 2019). "Interestingly, a dysregulation of aquaporin 2 is observed in renal failure or diabetic nephropathy." (PMID 40885721, 2025). "Research using a rat model revealed that mice with ischemia/reperfusion-induced acute kidney injury (AKI) had reduced levels of urine exosomal AQP-1 and AQP-2 protein and mRNA." (PMID 40305328, 2025). "In kidney pathophysiology, NFAT5 expression declines alongside AQP2 and endothelial NOS (eNOS) in the renal medulla during acute kidney injury in rodent models, emphasizing the importance of spatiotemporal regulation in renal injury progression." (PMID 40421201, 2025). "Also, the release of uEV-AQP1 and -AQP2 was decreased in models of acute kidney injury (AKI) including gentamicin- and renal ischemia-induced injury models in rats." (PMID 30744167, 2019).
acute kidney injury (continued). "Next, we compared the abundance of principal cell-specific AQP2 in uEVs from kidney transplant recipients without and with acute kidney injury." (PMID 39334890, 2024). "The objective of the present study was to compare principal cell-specific aquaporin-2 (AQP2) abundances in urinary extracellular vesicles (uEVs) on the first postoperative day in deceased-donor kidney transplant recipients without and with acute kidney injury." (PMID 39334890, 2024). "The objective of the present study was to compare principal cell-specific aquaporin-2 (AQP2) abundances in uEVs on the first postoperative day in deceased-donor kidney transplant recipients without and with acute kidney injury." (PMID 39334890, 2024). "Regarding transporters, we can mention that aquaporin 2 has been detected in rat and human urine and it has been used as a marker for different pathologies and that isoform 3 of the Na+-H+ exchanger NHE3 has been proposed as acute renal failure marker." (PMID 24199190, 2013). "To determine the cellular source of the increased uEV abundance in the patients with acute kidney injury, we analyzed the uEV abundance of proximal tubular expressed sodium-glucose transporter 2 (SGLT2), distal tubular expressed sodium/chloride cotransporter (NCC), and principal cell-specific AQP2." (PMID 39334890, 2024). "It is difficult to find information about the influence of soy isoflavones on AQP2 or AVPR2 in the literature, but there is information about other natural compounds such as triterpenoids that have been shown to downregulate renal AQP2 to protect against renal failure." (PMID 38791455, 2024).
diabetes (17 papers, 2013 to 2025). "An increase in water intake and urine flow has been reported for a rat model of diabetes mellitus, and this was associated with changes in inner‐medullary AQP2, phosphorylated AQP2 and AQP3 expression." (PMID 31691500, 2019). "The present results suggest that the decreased expression and activity of NOS in collecting ducts could be, at least in part, the cause of the AQP2 decreased expression in this model of diabetes induced by STZ." (PMID 25111608, 2014). "At the FAIM2 locus on chr 12q13.12, we observed known genes associated with obesity, eating patterns, and diabetes-related traits, including ASIC1, AQP2, AQP5, AQP6, RACGAP1, and AC025154.2 (AQP5-AS1) along with FAIM2." (PMID 39813287, 2025). "As with AQP1, the results for AQP2 expression in animals with induced (by STZ) diabetes are contradictory." (PMID 38791455, 2024). "AQP2 and UT-A1 proteins were up-regulated in the renal medulla collecting duct in diabetes for fighting against urine-concentrating defect." (PMID 37187875, 2023). "AQP2 as a member of the aquaporin family was mainly identified to be involved in the development of congenital nephrogenic diabetes insipidus, diabetes mellitus or heart disease." (PMID 36117171, 2022). "Our results show that in early diabetes, both AQP2 protein and mRNA are decreased and that L-Arg administration prevented these decreases in the renal outer medulla of diabetic rats." (PMID 25111608, 2014). "Our study shows that NO production, NOS I and NOS III expression, NOS activity and AQP2 expression are decreased in the renal outer medulla of rats at an early stage of STZ-induced diabetes." (PMID 25111608, 2014). "Earlier studies show that compensatory Aqp2 protein abundance increases in rats with streptozotocin-induced diabetic mellitus, which apparently differs from the present results." (PMID 23326416, 2013). "Furthermore, S. rebaudiana metabolites modulate antioxidant signaling pathways in the kidneys (Nrf2/Keap1) and the expression of aquaporin-2 (AQP2), alleviating metabolic disturbances and renal damage induced by diabetes." (PMID 40978487, 2025). "In this work, we analyzed the urine excretion of AQP5 and AQP2 (uAQP5 and uAQP2), via exosomes, in 35 diabetic patients: 12 normoalbuminuric with normal renal function (DM), 11 with proteinuric nondiabetic nephropathy (NDN), and 12 with histological diagnosis and classification of DN." (PMID 28246612, 2017). "Our hypothesis was that AQP2 expression is already decreased in diabetic animals at an early time point after induction of diabetes and that L-Arg supplementation improves NO production, which, in turn, increases AQP2 expression." (PMID 25111608, 2014). "The aim of this study was to evaluate whether L-Arginine (L-Arg) supplementation modifies nitric oxide (NO) system and consequently aquaporin-2 (AQP2) expression in the renal outer medulla of streptozotocin-diabetic rats at an early time point after induction of diabetes." (PMID 25111608, 2014). "Other studies have analyzed the urine levels of AQP5 and AQP2 excreted by exosomes in 35 patients with diabetes, suggesting that exosomal AQP5 and AQP2 may be used as novel noninvasive biomarkers to help classify the clinical stages of DN." (PMID 35395948, 2022). "Diabetes mellitus induces the upregulation of AQP2, even in the absence of vasopressin, to prevent excessive water loss." (PMID 30941057, 2019).
Hypokalemia (17 papers, 2013 to 2025). An abnormally decreased potassium concentration in the blood. "Critically, these two biochemical hallmarks, hypokalemia and hypercalciuria, act synergistically to induce a functional aquaporin-2 (AQP2) deficiency in the collecting duct, which is central to the siNDI phenotype." (PMID 41393191, 2025). "In the kidney, this results in abnormal activation of ROMK, ENaC, and AQP2 channels, exacerbating water and sodium retention as well as potassium loss, ultimately leading to hypertension with hypokalemia." (PMID 40949145, 2025). "Hypokalemia and hypercalcemia cause down-regulation of AQP2, which results in a vasopressin-resistant urinary concentrating defect." (PMID 34884753, 2021). "CKD was a chronic disease characterized by hypertension, urinary concentrating abnormalities, and electrolyte imbalances which including polyuria, hypercalcemia, hypernatremia, and hypokalemia caused by changes in AQP2 and AVPR2 expression." (PMID 34903939, 2021). "The impairment of the autophagic lysosomal degradation of total-AQP2 and pS261-AQP2 in hypokalemia caused a severe urinary concentration defect." (PMID 30816234, 2019). "Moreover, hypokalemia has been shown to cause autophagic degradation of AQP2 channels, leading to impaired water reabsorption even in the presence of ADH and inducing downregulation of this channel expression." (PMID 40625516, 2025). "Hypercalciuria, hypokalemia, and renal tubular acidosis are associated with decreased expression of AQP2, and may also have been involved in the mechanism of NDI in this case." (PMID 29901649, 2018). "Hypokalemia directly reduces the total abundance of AQP2 water channels by promoting their autophagic-lysosomal degradation." (PMID 41393191, 2025). "Concurrently, the classic BS features of chronic hypokalemia and hypercalciuria directly impair the final step of water reabsorption by downregulating and inhibiting the aquaporin-2 (AQP2) water channels in the collecting duct, rendering it resistant to AVP." (PMID 41393191, 2025). "This suggested a transient vasopressin-resistant state, possibly due to hypokalemia-induced downregulation of the aquaporin-2 (AQP2) channel in the renal collecting ducts." (PMID 40625516, 2025). "Rather than a fixed genetic defect in water conservation, it is a dynamic, reversible phenotype driven by prostaglandin-mediated hypokalemia and hypercalciuria, which secondarily impair AQP2 function." (PMID 41393191, 2025). "In this study, we examine the role of canonical or non-canonical autophagy in the degradation of AQP2, with particular focus on pS256- and pS261-AQP2 in induced prolonged hypokalemia." (PMID 30816234, 2019). "Taken together, these findings indicated that the down-regulation of AQP2 in hypokalemia was induced by a reduction of protein level, by redistribution of pS261-AQP2 into the intracellular vesicles, and by a reduction of apical plasma labeling of pS256-AQP2." (PMID 30816234, 2019). "In summary, our results demonstrated that urinary concentrating defect in hypokalemia is induced by reduced AQP2 phosphorylation, resulting in a reduction of apical labeling of pS256-AQP2." (PMID 30816234, 2019). "In response to hypokalemia from a K+-restricted diet for 2 weeks, total-AQP2 and pS261-AQP2 were redistributed from the apical or subapical domains to intracellular LC3-positive autophagic vacuoles." (PMID 30816234, 2019). "To investigate the effect of hypokalemia on the expression and distribution of AQP2, we performed western blot analyses and immunohistochemical staining for total-AQP2, pS256-AQP2, and pS261-AQP2 after K+-depletion for 2 weeks." (PMID 30816234, 2019). "Rather, pS261-AQP2 demonstrates a similar redistribution pattern as total AQP2, suggesting that pS261-AQP2 is subject to the same degradation pathway as total AQP2 as a consequence of hypokalemia." (PMID 30816234, 2019).